ANKRD13A (ankyrin repeat domain 13A)
Description:
Ubiquitin-binding protein that specifically recognizes and binds 'Lys-63'-linked ubiquitin. Does not bind 'Lys-48'-linked ubiquitin. Positively regulates the internalization of ligand-activated EGFR by binding to the Ub moiety of ubiquitinated EGFR at the cell membrane.
Synonyms: ANKRD13; NY-REN-25
Tractability: Antibody: UniProt places it where antibodies can reach, with high confidence; its Gene Ontology location is reachable by antibodies, with high confidence; the Human Protein Atlas places it where antibodies can reach. PROTAC: UniProt records ubiquitination sites on it; ubiquitination databases record sites on it; its protein half-life has been measured.
Gene: Protein-coding gene on chromosome 12 (109,999,186 to 110,039,763, forward strand). Ensembl gene ENSG00000076513.
Subcellular location: Cell membrane; Late endosome
Subcellular location (Human Protein Atlas): Plasma membrane; Primary cilium; Primary cilium tip; Primary cilium transition zone; Vesicles
Gene Ontology:
Molecular function: ubiquitin-modified protein reader activity
Biological process: negative regulation of protein localization to endosome; negative regulation of receptor internalization; regulation of receptor-mediated endocytosis
Cellular component: cytoplasm; late endosome; perinuclear region of cytoplasm; plasma membrane
Genetic constraint (gnomAD): Loss-of-function variants: 42 observed, 75.46 expected, observed/expected ratio (o/e) 0.56, 90% interval 0.43 to 0.72. The upper end of that interval is the gene's LOEUF score, 0.72, which puts it in group 2 of 6, group 1 being the genes least tolerant of losing a copy. Missense variants: 576 observed, 706.35 expected, observed/expected ratio (o/e) 0.82, 90% interval 0.76 to 0.87. Synonymous variants: 212 observed, 255.18 expected, observed/expected ratio (o/e) 0.83, 90% interval 0.74 to 0.93.
Homologues: Orthologues: chimpanzee ANKRD13A (100% identical), macaque ANKRD13A (99% identical), dog ANKRD13A (94% identical), guinea pig ANKRD13A (94% identical), rabbit ANKRD13A (94% identical), rat Ankrd13a (91% identical), mouse Ankrd13a (91% identical), pig ANKRD13A (85% identical), tropical clawed frog ankrd13a (69% identical), zebrafish ankrd13a (65% identical), Drosophila melanogaster CG15118 (41% identical), Caenorhabditis elegans C18F10.7 (33% identical). Paralogues in human: ANKRD13D (55% identical), ANKRD13B (53% identical), ANKRD13C (29% identical).
Diseases named in the same sentence as ANKRD13A in open-access papers:
ANKRD13A is named in the same sentence as 6 diseases in open-access papers, as found by Europe PMC text mining. Sharing a sentence is not in itself a finding about the gene and the disease. The quoted sentences say what the papers report.
acute myeloid leukemia (3 papers, 2022). Acute myeloid leukemia (AML) is a group of neoplasms arising from precursor cells committed to the myeloid cell-line differentiation. "Through regulating USP30 and ANKRD13A, USP30-AS1 suppressed the apoptosis of acute myeloid leukemia cells, and therefore improved cell viability." (PMID 35260141, 2022).
cancer (4 papers, 2020 to 2025). A tumor composed of atypical neoplastic, often pleomorphic cells that invade other tissues. "We also identified the top 1 GEAR in individual cancer types, such as TLL1 (BLCA), PGK1 (BRCA), RFXANK (CESC), DPP7 (COAD), VWA8 (KIRC), SCMH1 (LGG), HILPDA (LIHC), TLE1 (LUAD), CD151 (LUSC), ANKRD13A (OV), SOCS2 (PAAD), DRG2 (PRAD), ADAMTS6 (STAD), PSMB8 (THCA), ASS1 (UCEC)." (PMID 41404730, 2025). "Knockdown of USP30, but not ANKRD13A, abolished the cancer-promoting effects of USP30-AS1." (PMID 34694569, 2022).
tumor (2 papers, 2022). "At the same time, USP30-AS1 can also target ANKRD13A to affect the translocation of HLA-Iprotein from cell membrane to cytoplasm, probably leading to the tumor immune escape." (PMID 34694569, 2022).
infection (1 paper, 2023). The state of being infected such as from the introduction of a foreign agent such as serum, vaccine, antigenic substance or organism. "To this end, we employed MS to identify ANKRD13A as a novel ubiquitinated protein during Tg infection in IFNγ-stimulated epithelial cells." (PMID 37975677, 2023). "We show that a host protein, ANKRD13A, is ubiquitinated on host cell infection by Tg type II Pru." (PMID 37975677, 2023). "Apoptotic cell death is employed in response to Tg infection of human macrophages as a mechanism of infection control, and it is conceivable that cellular interactions involving ANKRD13A may skew the response to Tg infection in different cell types." (PMID 37975677, 2023). "Recruitment of total ubiquitin, p97/VCP, ANKRD13A, and UBXD1 at 2 h was determined at the PV in cells pre-stimulated with IFNγ and then treated for 2 h with the E1 enzyme inhibitor, PYR41, prior to infection with Tg type II Pru." (PMID 37975677, 2023). "Convergent deposition of ANKRD13A, p97/VCP, and UBXD1 onto the same vacuole is dependent on vacuolar ubiquitination and observed within 2 h post-infection." (PMID 37975677, 2023).
ANKRD13A also shares sentences with these, for which no sentence is quoted: colorectal cancer (1 paper); neuroblastoma (1).